PTGS2 (prostaglandin-endoperoxide synthase 2)
Diseases named in the same sentence as PTGS2 in open-access papers (continued):
Sharing a sentence is not in itself a finding about the gene and the disease.
ovarian carcinoma (36 papers, 2006 to 2025). A malignant neoplasm originating from the surface ovarian epithelium. "One study reported that concurrent increased expression of ADRB2 and PTGS2 in ovarian cancer was associated with poor survival, suggesting activation of this axis should be explored as a biological pathways driving disease spread, leading to residual disease." (PMID 36761962, 2023). "Noradrenaline increased the PTGS-2 and PTGES mRNA/protein expression and the PGE2 release from human ovarian cancer cells and PTGS-2 mRNA/protein expression and PGE2 secretion from lipopolysaccharide (LPS)-induced rat primary microglia." (PMID 36982930, 2023). "PTGS2 enhanced the proliferation and migration of human ovarian cancer CAOV-3 cells mainly by activating phosphatidylinositol 3 kinase/protein kinase B (PI3-k/Akt) pathway." (PMID 35411258, 2022). "The PTGS2 protein level is modulated by beta-2 adrenergic receptor (ADRB2) receptor signaling, and PTGS2 silencing suppresses migration and invasion of ovarian cancer cells." (PMID 33921245, 2021). "Notably, the S01 NK cell state was significantly lower in the PTGS2/CTLA4-high group in the TCGA ovarian cancer dataset." (PMID 38201508, 2023). "This further indicates the mechanism of the Danshen-Guizhi drug pair in the treatment of ovarian cancer may be inhibiting the expression of PTGS2." (PMID 35411258, 2022). "However, there are also reports in human and rats that LPA increased PGE2 synthesis in human monocytic and ovarian cancer cells as well as rat mesangial cells via upregulation of PTGS2." (PMID 24744506, 2014). "PDE10A and PTGS2 were significantly decreased, but ITGB7 was significantly increased in ovarian cancer." (PMID 38714753, 2024). "Utilizing the PTGS2/CTLA4 ratio, we stratified samples into high- and low-expression groups based on the median ratio to evaluate the impact on survival in multiple ovarian cancer cohorts." (PMID 38201508, 2023). "ACSL1 and FSP1 expression was significantly higher in metastatic tumors in the omentum than in tumors of the normal ovary and in primary ovarian cancer, while the expression of 4-HNE and PTGS2 was lower in the omentum metastasis tumor." (PMID 36882396, 2023). "The OS of ovarian cancer patients prolonged with the high-expression of ATG7, G6PD, SLC3A2, MAP1LC3C and PTGS2, but shrank with the increased expression of NFS1, VDAC2, ACSL3." (PMID 35039008, 2022). "Our study shows that PTGS1 (COX1) is significantly positively correlated with ovarian cancer prognosis, while PTGS2 is not significantly correlated with ovarian cancer prognosis." (PMID 38651149, 2024). "We found that the total count of activated NK cells (estimated by MIXTURE) was higher only in the PTGS2/CTLA4-low group from the ovarian cancer TCGA cohort, but not for the AOCS cohort." (PMID 38201508, 2023). "It was reported that noradrenaline could activate β2-ARs and transcriptionally activate PTGS-2 and PTGES via nuclear factor-kappaB (NF-kappaB) to produce PGE2 in human ovarian cancer cells." (PMID 36982930, 2023).
Stroke (36 papers, 2012 to 2025). Sudden impairment of blood flow to a part of the brain due to occlusion or rupture of an artery to the brain. "Studies have shown thatpolymorphism in the PTGS2 gene reduces the risk of myocardialinfarction and stroke by affecting COX-2 activity and reducing the formation ofatherosclerotic plaques (Cipollone etal., 2004)." (PMID 29658970, 2018). "In the Atherosclerosis Risk in Communities (ARIC) study and one other study, the C allele of PTGS2 rs20417 was reported to be associated with higher risk of stroke in African Americans or Brazilian population." (PMID 28704403, 2017). "Through network pharmacology and computational simulations, key targets associated with musk volatile compounds and stroke, including SRC, EGFR, ESR1, PTGS2, and DRD2, were identified." (PMID 40137146, 2025). "Our findings indicate that the upregulation of Ptgs2, Lgals3, Il6r, and Jak3 further enhances the inflammatory response following stroke." (PMID 39847586, 2025). "Consistent with our study, Ptgs2 expression is significantly increased in stroke with inflammatory cell infiltration, and related studies have reported a correlation between Ptgs2 and IS36." (PMID 37563282, 2023). "The important biological targets for network pharmacological analysis of TM-CX and TM-JH related to stroke were PTGS2, ACE, APP, NOS1, and NOS2." (PMID 32328128, 2020). "The C allele of PTGS2 rs20417 was reported to be associated with COX-2 activity and higher risk of stroke in African Americans." (PMID 28704403, 2017). "In addition, network pharmacological analyses identified 180 potential targets of the major volatile compounds of musk associated with stroke, and five key targets (SRC, EGFR, ESR1, PTGS2, and DRD2)." (PMID 40137146, 2025). "It has been shown that PTGS2 is associated with carotid plaque, platelet activation, and TXA2 levels and is a target for the effects of smoking and alcohol consumption on stroke, and inhibition of PTGS2 can have a protective effect on MCAO mice through the NF-κB signaling pathway." (PMID 34603472, 2021). "Calcium signaling pathway-related genes (AC079305.10, BCL10, BCL2A1, BRE-AS1, DYNLL2, EREG, and PTGS2) are related to apoptosis after stroke, whereas posttranscriptional regulation of BCL2A1 may be possibly associated with IS." (PMID 34987704, 2021). "We evaluated the potential value of 4 key hub genes (ADM, PTGS2, VCAN, and MMP9) in stroke diagnosis." (PMID 39519172, 2024). "Based on the 95 crossover genes identified, PPI network analysis uncovered six core genes including MMP9, MAPK3, PTGS2, JUN, IL1B and TNF likely linking the activity of luteolin to effective stroke control." (PMID 34898370, 2021). "In anti-stroke target analysis of the total group, the results showed that IL1B, IL8, JUN, MMP9 and PTGS2 were significantly up-regulated." (PMID 27672514, 2016). "Therefore, SRC, EGFR, ESR1, PTGS2, and DRD2 are closely related to the occurrence and development of stroke, and the volatile compounds of musk may treat nerve damage caused by stroke by binding to these key target proteins." (PMID 40137146, 2025). "In the same vein, JAK3 inhibition with 10 mg/kg decernotinib did not affect stroke-induced upregulation of Ccl2, Cxcl10, and Cxcl1, chemokines important for immune cell trafficking, nor proinflammatory mediators IL-1β, IL-6, Tnfα, Ptgs2, and Mmp-9 that exacerbate stroke damage." (PMID 28790974, 2017).
asthma (34 papers, 2012 to 2026). "We identified 31 potential targets associated with AFB1 exposure and asthma, including PTGS2, ADRB2, CysLTR1, PTGS1, and others." (PMID 41557720, 2026). "CASP3 may play a role in allergic asthma; the PTGS2 gene is associated with diisocyanate-induced asthma." (PMID 33178315, 2020). "We identified 31 potential targets that may be associated with AFB1 exposure and asthma, including PTGS2, ADRB2, CysLTR1, PTGS1, and others, which play crucial roles in airway inflammation, smooth muscle contraction, immune regulation, and inflammatory mediator production." (PMID 41557720, 2026). "Cyclooxygenase-2 (COX-2), also known as prostaglandin-endoperoxide synthase-2 (PTGS2), is an enzyme that has been implicated in asthma and fibrosis." (PMID 33022979, 2020). "Further investigation revealed several lipid-associated enzymes implicated in asthma pathogenesis to be encompassed by asthma-SEs (e.g., PTGS1, PTGS2, CYP24A1)." (PMID 33362848, 2020). "Ferroptosis can directly increase PTGS2 expression and promote the release of inflammatory signaling molecules, which may contribute to the amplification of inflammatory responses in asthma." (PMID 41557720, 2026). "Clinical studies have shown that, compared with healthy subjects, asthma patients have significantly elevated PTGS2 levels in their bronchoalveolar lavage fluid, suggesting it could be an important biomarker of asthma inflammation activation." (PMID 41557720, 2026). "Prostaglandin-Endoperoxide Synthase 2 (PTGS2) plays a significant role in asthma and COPD, and its upregulation results in the production of mediators such as prostaglandins and further promotes airway inflammation, increasing symptoms of allergic asthma as well as exacerbations of COPD." (PMID 40160461, 2025). "However, bronchoalveolar lavage analysis revealed a significant decrease in PTGS2 levels in moderate and severe asthma cases." (PMID 40160461, 2025). "Although COX2 (PTGS2) is usually considered to induce inflammation, previous studies have found that COX-2 deficient mice, or those treated with COX inhibitors, display exaggerated inflammatory responses in the lungs, leading to the development of asthma." (PMID 38549670, 2024). "PTGS2, as the most critical target in the network, is one of the key factors of cell response to inflammation and has long been considered to play a key role in the pathogenesis of respiratory inflammation, including asthma." (PMID 35586697, 2022). "Other studies have shown that PTGS2 is a downstream target of NF-κB and that NF-κB phosphorylation upregulates PTGS2 expression in airway epithelial cells and smooth muscle cells, thereby promoting the release of inflammatory mediators, making it a key step in the pathogenesis of asthma." (PMID 41557720, 2026). "PPI network analysis showed that PTGS2, BCL2, and CASP3 were the key predictive targets of QJWJ in treating asthma." (PMID 39889171, 2025). "PTGS2, IL10, CTSB, JAK2, and MTOR were significantly downregulated in alveolar lavage fluid with increasing asthma severity, while MMP9, GSK3B, BCL2, EGFR, and CCND1 were upregulated." (PMID 40160461, 2025). "Our results demonstrate that these phthalates affect the pathogenesis of asthma and COPD by modulating various target genes, including PTGS2, MMP9, and CASP3, which are involved in essential biological pathways such as apoptosis and immune response." (PMID 40160461, 2025). "Quercetin, luteolin, linolenic acid, adenosine, kaempferol, etc., were considered the potential core compounds, and PTGS2, ESR1, PTGS1, NOS2, AKT1, etc. were the main potential targets of BSYQ for asthma and IPF therapy." (PMID 35672815, 2022). "The PPI network, which had 31 nodes and 68 edges, was constructed using the intersection of AFB1 and asthma target genes In this study, PTGS2, ADRB2, MMP9, CysLTR1, and PTGS1 were the top five targets according to degree value, representing the hub targets of AFB1-induced asthma." (PMID 41557720, 2026).
asthma (continued). "Furthermore, this study utilized network pharmacology to identify pivotal asthma treatment targets for YKS, including AKT1, TNF, IL1B, EGFR, IFNG, IL4, CASP3, and PTGS2." (PMID 40420184, 2025). "However, beyond these observational studies, mechanistic studies analyzing the role of PTGS2 and PGE2 in the human bronchial epithelium in asthma are limited." (PMID 38179897, 2024). "In contrast, neither PTGS2 expression nor PGE2 release were increased under the same conditions using cells cultured from donors with severe asthma." (PMID 38179897, 2024). "Additionally, three asthma drugs undergoing clinical trials were found to interact with FCGR3A, despite targeting TNF (adalimumab and etanercept) and PTGS1/PTGS2 (indomethacin)." (PMID 37875944, 2023). "Interestingly, FP alone significantly reduced several pro-inflammatory genes related to ASM and asthma, including IL-6, MMP1, PTGS2, and TNFSF15." (PMID 35578269, 2022). "Our subsequent molecular docking showed that each bioactive compounds (quercetin, wogonin, luteolin, naringenin, and kaempferol) of MGMD has favorable binding abilities with STAT3, PTGS2, JUN, VEGFA, EGFR, and ALOX5, further arguing the potential molecular mechanism of action of MGMD in asthma." (PMID 33968984, 2021). "PTGS2 inhibition seemed to have a negative effect on both diseases, while PTGS1 was overrepresented only among targets of drugs contraindicated in asthma." (PMID 31705029, 2019).
Hypertension (34 papers, 2013 to 2025). The presence of chronic increased pressure in the systemic arterial system. "Like Ptgs2, Rarres2 is also known to regulate inflammation and has been linked with hypertension, a known risk factor of aortic valve stenosis." (PMID 29740591, 2018). "Apart from Mmp11 which is a matrix metalloproteinases as Mmp2 we selected Ptgs1, Ptgs2 and Olr1 due to their possible relation to the vascular changes associated with hypertension." (PMID 28880918, 2017). "Among the 34 BP signature genes (at Bonferroni corrected p<0.05), only FOS and PTGS2 have been previously implicated in hypertension." (PMID 25785607, 2015). "Furthermore, the inflammation is characterized by increased levels of local inflammatory cytokines such as TNF, IL10, and PTGS2, which are more likely to be useful diagnostic tools for hypertension in the future." (PMID 35308213, 2022). "Six genes (PTGS2, TBXA2R, ZNF101, KCNJ2, MSRA, and CMTM5) have been reported to be associated with hypertension." (PMID 39854379, 2025). "Changes in several genes, including JAK2, PTGS2, and HIF1A, which have also been connected to the emergence of hypertension, have been linked to resistance to these inhibitors." (PMID 37571339, 2023). "Additionally, numerous drugs target PTGS2 for intervention in the treatment of hypertension and other cardiovascular diseases." (PMID 39854379, 2025). "Current research has shown a correlation between PTGS2 and hypertension." (PMID 39854379, 2025). "Our findings also showed elevated PTGS2 expression in the aorta of Ang II-infused hypertensive mice, which was reversed by treatment with α-MG, indicating that PTGS2 not only served as a critical player in molecular mechanism of hypertension but also as a therapeutic target of α-MG." (PMID 39592923, 2024). "Based on the results of the network analysis and molecular docking, we found that AKT1, VEGFA, eNOS, ICAM-1, PTGS2, and ALB may also be associated with the potential effects of GZD on hypertension." (PMID 33906674, 2021). "We have also identified 8 important genes (NME4, PNPLA7, GGT5, PTGS2, IGF1R, NT5C2, ENTPD1 and PTEN), a number of gene ontology categories and biological pathways that may be associated with military pilot hypertension." (PMID 29996846, 2018). "We have also identified 8 important genes (NME4, PNPLA7, GGT5, PTGS2, IGF1R, NT5C2, ENTPD1 and PTEN), a few GO categories and biological pathways that may be associated with the military pilot hypertension." (PMID 29996846, 2018). "Therefore, equol may act as a PTGS2 inhibitor for the treatment of hypertension." (PMID 39433698, 2024). "In the PPI network, a total of 14 targets, such as TNF, CHRM1, ACE, IL10, PTGS2, REN, and F2, were the hub targets of MVO for treating hypertension." (PMID 35308213, 2022). "For example, puerarin can have an effect on 45 targets, such as VEGFA, PTGS2, AR, PPARG, and RELA, when treating hypertension." (PMID 32265716, 2020). "The results from Western blotting showed that NME4 and PNPLA7 these two genes were up-regulated significantly and GGT5, PTGS2, IGF1R, NT5C2, ENTPD1 and PTEN these six genes were down-regulated significantly in PBMCs of military pilots with hypertension." (PMID 29996846, 2018). "Our analyses showed that TNF, HSP90AA1, NFKB1, PPARG, SIRT1, PTGS2, and RELA might be α-MG’s potential therapeutic targets for hypertension, laying groundwork for further investigation into its pharmacological mechanisms and clinical uses." (PMID 39592923, 2024). "The results indicate that in the Ang II-induced hypertension group, the expression levels of TNF, NFKB1, MAPK3, PTGS2, and RELA were markedly elevated compared to the control group, while the expression levels of HSP90AA1, HSP90AB1, PPARG, SIRT1, MAPK1, and PRKCA were significantly decreased." (PMID 39592923, 2024).
Hypertension (continued). "Moreover, the results highlighted the idea that MVO could regulate the expression levels of targets, especially for TNF, CHRM1, ACE, IL10, PTGS2, REN, and F2, as well as neuroactive ligand–receptor interaction, the calcium signaling pathway, and PI3K-Akt signaling pathway to treat hypertension." (PMID 35308213, 2022).
myocardial infarction (33 papers, 2005 to 2025). Gross necrosis of the myocardium, as a result of interruption of the blood supply to the area, as in coronary thrombosis. "Myocardial infarction is closely associated with hypoxia-related genes such as SELP, CXCL2, MyD88, and S100a8 and genes related to Atf3, PTGS2, Cxcl1, and Socs3 ferroptosis." (PMID 37181809, 2023). "Study finds that miR-26b can improve myocardial remodel and reduce the inflammatory response in mice with myocardial infarction via inhibiting PTGS2 to activate the MAPK pathway." (PMID 34286341, 2021). "Interestingly, suppressing Ptgs2 expression in myocardial infarction models can mitigate cardiomyocyte ferroptosis, reducing tissue damage." (PMID 38254192, 2024). "The exact chelation mechanism is unknown, but dexrazoxane significantly increased the expression level of Ptgs2 mRNA, which further led to a reduction in the myocardial enzyme spectrum and the scar area of myocardial infarction." (PMID 37629039, 2023). "One notable example somewhat further down the list was PTGS2 (COX2), which was rated in the top 2% for likely toxicity and is the key protein target, leading to high-profile withdrawal of Vioxx drug because of the doubling of heart attack risk." (PMID 30515477, 2018). "GAA remarkably reduces myocardial infarct size, decreases lipid peroxidation, activates NRF2, and downregulates levels of PTGS2 and ACSL4 in both mRNA and protein." (PMID 37629039, 2023). "It has been demonstrated that inhibiting PTGS2 activates the MAPK pathway, thereby reducing the inflammatory response and improving myocardial remodeling in mice with myocardial infarction." (PMID 36873789, 2023). "The expression of ACSL4, LAMP2, PTEN, PTGS2, and SAT1 were different in the early and late stages of myocardial infarction." (PMID 36407421, 2022). "Our data clarified that FA improved oxidative stress, reduced ROS overproduction, promoted GSH production, inhibited Ptgs2 mRNA and Fe2+ accumulation, declined LDH and CK activities, attenuated myocardial infarction, and ameliorated I/R-induced ferroptosis." (PMID 34935700, 2021). "Nevertheless, no major clinical trials of PTGS2 inhibitors were completed in CRC due to their adverse effects, such as elevated risk of myocardial infarction, dyspepsia, abdominal pain, gastrointestinal bleeding, and gastritis." (PMID 38778047, 2024). "Analysis of human blood sample sequencing datasets and mouse myocardial infarction sequencing datasets as well as cardiomyocyte hypoxia experiments indicated that FRGs ALOX5, CAMKK2, KDM6B, LAMP2, PTEN, PTGS2, and ULK1 may be potential biomarkers of AMI." (PMID 36407421, 2022).